TSC1 (TSC complex subunit 1)
Diseases named in the same sentence as TSC1 in open-access papers (continued):
Sharing a sentence is not in itself a finding about the gene and the disease.
PEComas (41 papers, 2011 to 2026). "Molecular alterations in uterine PEComas frequently involve dysregulation of the mTOR signaling pathway, most often due to inactivating mutations in the TSC1 or TSC2 genes." (PMID 41463261, 2025). "While studies on the pathogenesis of PEComas have largely established the role of the 2 main genomic drivers (TSC1/2 loss and TFE3 fusions), recent work has further characterized their interdependence." (PMID 41044182, 2025). "Unfortunately, mTOR inhibitors do not appear to improve PFS relative to standard chemotherapy regimens or provide OS benefit in TSC1/TSC2 mutated malignant PEComas." (PMID 40900800, 2025). "Molecular alterations in conventional PEComas often involve mutations, copy number losses, or rearrangements in the TSC1 or TSC2 genes, and they are reported in up to 90% of cases." (PMID 40647483, 2025). "PEComas with TSC1/2 mutations or TFE3 rearrangements respond to mTORC1 inhibition, while IMTs harboring ALK, RET, PDGFRB, or NTRK rearrangements demonstrate marked responses to ALK or TRK inhibitors." (PMID 41463261, 2025). "PEComas frequently contain TSC1 or TSC2 mutations, leading to aberrant activation of the mTOR pathway." (PMID 41463261, 2025). "According to many experts in this field, PEComas are seen at a high frequency in the tuberous sclerosis complex due to inactivating germline mutations TSC1/TSC2 (tuberous sclerosis complex 1/2)." (PMID 38535035, 2024). "The presence of melanin pigment in some renal TFE3-rearranged PEComas has been considered a distinctive feature from PEComas carrying TSC1/2 mutations, leading some authors to propose reclassifying them as “melanotic Xp11 neoplasms”." (PMID 39410016, 2024). "PEComas often harbor somatic inactivating mutations in either TSC2 or TSC1, and patients with tuberous sclerosis complex, who carry germline mutations in these genes, often develop various types of PEComas during their lifetime." (PMID 37448552, 2023). "Perivascular epithelioid cell tumors (PEComas) are associated with mutations in TSC1 and TSC2 with subsequent activation of the mTOR pathway." (PMID 35626152, 2022). "The majority of PEComas have a loss of function (LOF) of TSC-1 or -2 genes (commonly TSC-2 LOF), leading to increased mTOR pathway activation." (PMID 36360169, 2022). "A subset of malignant PEComas are associated with mutations (inactivation or deletions) of TSC1 or TSC2, negative regulators of the mTOR signaling pathway." (PMID 34637337, 2021). "Ninety-one percent (10 of 11) of PEComas with TSC1 or TSC2 mutations were pS6+, whereas only 44% (5 of 11) without TSC1 or TSC2 mutations were pS6+ (Fisher's exact P = .06)." (PMID 34637337, 2021). "Regarding molecular characteristics, PEComas are characterized by mutations leading to mTOR pathway activation, such as TSC1 or TSC2 bi-allelic inactivation, TFE3 gene fusion and FLCN truncating mutations." (PMID 34680376, 2021). "The activation of the mTOR pathway through the loss of the tuberous sclerosis complex 1 (TSC1)/TSC2 repressor complex seems to be a common pathogenic event in PEComas." (PMID 34542724, 2021). "Generally, in conventional advanced PEComas pathologically activated by the loss of the TSC1/TSC2 tumor suppressor complex, mTOR1 is a rational mechanistic target for the therapy with its inhibitors, such as rapamycin or everolimus." (PMID 31103952, 2019). "PEComas are associated with mutations or deletions of tuberous sclerosis associated genes TSC1 or TSC2, which act as tumor suppressor genes by regulating mTOR." (PMID 21846376, 2011). "Longer-term therapeutic responses with significantly improved efficacy over chemotherapy can be achieved with mTOR inhibitors in malignant PEcoma, especially in patients with mutations in the TSC1/TSC2 genes that result in aberrant activation of the mTOR pathway." (PMID 40989692, 2025). "Molecularly, most PEComas, harbor a loss of function of the TSC1/TSC2 complex." (PMID 38664269, 2024).
PEComas (continued). "Therefore, the immunoprofile of renal and extrarenal TFE3-rearranged PEComas overlaps, but it slightly differs from PEComas related to TSC1/TSC2 mutations, in which the expression of muscle markers, particularly actin, is more frequently observed." (PMID 39410016, 2024). "The most common genetic alteration present in sporadic or hereditary PEComas is a loss of function of the TSC1 (~ 27%) or TSC2 (~ 73%) genes, leading to the activation of mTOR signaling, which may represent a therapeutic target." (PMID 38243242, 2024). "In humans, PEComas generally have mutations in the TSC1/TSC2 genes, but MiT/TFE translocations have been observed when those are absent, suggesting that the pathways may converge, which is consistent with our earlier pioneering studies." (PMID 38386415, 2024). "Conventional PEComas harbor mutations and loss of heterozygosity (LOH) in the TSC2 gene and, more rarely, the TSC1 gene, which may be associated with angiomyolipomas and PEComas." (PMID 37470853, 2023). "Although most patients have sporadic PEComas, a subset may be associated with the inactivation of TSC1 or TSC2 genes and the occurrence of TFE3 gene fusions." (PMID 36367123, 2023). "Therefore, the two-hit mutation of TSC1 or TSC2 is causally associated with the onset of TSC-PEComas." (PMID 35928867, 2022). "Sporadic PEComas were also found to carry TSC1 or TSC2 somatic inactivating mutations." (PMID 34442003, 2021). "Moreover, in 10–20% of sporadic PEComas cases, loss of 9q34 (TSC1) or 16q13.3 (TSC2) has been reported." (PMID 34442003, 2021). "Molecularly, most PEComas are defined by a loss of function of the TSC1/TSC2 complex." (PMID 31309284, 2020). "Molecularly, most PEComas, including sporadic ones, are defined by a loss of function of the TSC1/TSC2 complex, in the majority of the cases the result of a loss of heterozygosity (LOH) in the TSC2 gene, leading to increased mTORC1 activation and deregulated cell growth signaling." (PMID 31309284, 2020). "Furthermore, such PEComas lack TSC1/TSC2 inactivating mutations of conventional PEComas and retain their protein expression according to immunohistochemistry data." (PMID 31103952, 2019). "Furthermore, a high percentage of de novo PEComas can have somatic mutations in the TSC1/2 complex." (PMID 36980578, 2023). "Molecularly, PEComas often harbor TSC1/TSC2 gene alterations leading to the activation of the mTOR signaling pathway." (PMID 41479435, 2026). "Malignant perivascular epithelioid cell tumors (PEComas) are rare tumors in which the PI3K/AKT/mTOR pathway is critical for pathogenesis and is often associated with mutations in the TSC1/TSC2 genes." (PMID 40989692, 2025). "Dysregulation of the mTOR signaling due to functional mutations or loss of TSC1 or TSC2 leads to abnormal cell growth and the development of PEComas." (PMID 39220642, 2024). "PEComas are most commonly found in females and often show either TSC1 or TSC2 alterations, which result in the activation of the mTOR pathway, or TFE3 fusions." (PMID 37041531, 2023). "In summary, this case highlights the importance of molecular analysis, particularly TSC1/2 alterations, for both the definitive diagnosis of malignant PEComas and predicting their response to nab-sirolimus." (PMID 37041531, 2023). "Two major molecular subgroups have recently been identified for PEComas: those with TSC1 or TSC2 alterations and those with TFE3 fusions." (PMID 37041531, 2023). "Although most PEComas harbor loss-of-function TSC1/TSC2 mutations, a small subset of PEComas show rearrangement of the TFE3 gene." (PMID 36647157, 2023). "Given these molecular characteristics, mTOR inhibitors have recently been approved by the FDA in the treatment of malignant PEComas, particularly in those with TSC1/2 alterations." (PMID 37041531, 2023). "Inhibition of hyperactivated mTORC1, which results from loss of the TSC1/TSC2 tumor suppressor complex, is a specific molecular target for PEComas therapy." (PMID 34442003, 2021).
PEComas (continued). "PEComas are associated with genetic alterations similar to those in TSC, an autosomal dominant genetic disease caused by the loss of TSC1 (9q34) or TSC2 (16p13.3) genes." (PMID 31103952, 2019). "Conversely, TSC1 mutation and LOH is rare in angiomyolipoma and perivascular epithelioid cell tumors." (PMID 29221145, 2017). "Taken together, these observations suggest that activation of mTOR through loss of the TSC1/TSC2 repressor complex, or potentially by other means, is likely a common and critically pathogenic event in PEComas." (PMID 22943457, 2012). "The prior literature also highlights TFE3 (transcription factor E3)-rearranged PEComas with a lack of TSC1/2-inactivating mutations." (PMID 38535035, 2024). "PEComas are usually associated with TSC-2 and rarely TSC-1 loss-of-function mutations." (PMID 34918628, 2021). "However, homozygous and/or heterozygous deletion of TSC1 or TSC2 generally does not induce the formation of renal AML in mice, although one previous mouse model of mosaic TSC1 deletion developed renal mesenchymal lesions that resembled human PEComas, with upregulated melanocytic marker expression." (PMID 41044182, 2025). "Most PEComas arise sporadically, but may be associated with tuberous sclerosis complex (TSC), an autosomal dominant genetic disorder characterized by germline mutations in the TSC1 or TSC2 genes." (PMID 38243242, 2024). "Most PEComas arise sporadically, but may be associated with tuberous sclerosis complex (TSC), an autosomal dominant genetic disorder that is caused by germline mutations in the TSC1 or TSC2 genes." (PMID 38243242, 2024). "Explaining the mutual exclusivity between TSC1/2 inactivation and MiT/TFE gene rearrangements in PEComas, we and others have previously shown that mTORC1 activation leads to constitutive activation of TFEB and TFE3 through FLCN inactivation." (PMID 41044182, 2025). "Interestingly, these PEComas are characterized by the absence of more common mutations in the TSC1 and TSC2 genes, which also alter TFE3/TFEB regulation, upon which the pathogenesis may converge." (PMID 38386415, 2024). "The most common genetic alterations in sporadic and hereditary PEComas demonstrate inactivation of the TSC2 (16p13.3) and the TSC1 (9q34) genes." (PMID 36367123, 2023). "Genetic studies have found that PEComa may occur as a sporadic disease or as a component of TSC (including TSC1 and TSC2), which suggests the oncogenesis of PEComas as a TSC-associated neoplasm." (PMID 31171030, 2019). "Even though access to molecular biology has increased since previous reviews, very few cases reported the search for a TFE3 translocation, a TSC1 or TSC2 loss of function mutations or even no FCLN mutation, considered to be the more recent genomic alterations described in PEComas." (PMID 34680376, 2021). "Recent studies demonstrated TSC1/2 inactivation and m-TOR hyperactivation in non-TSC AMLs and in extrarenal PEComas using immunohistochemistry and Western blot analysis." (PMID 22943457, 2012).
lymphangioleiomyomatosis (37 papers, 2014 to 2026). A multifocal neoplasm with perivascular epithelioid cell differentiation affecting almost exclusively females of child-bearing age. "Lymphangioleiomyomatosis (LAM) is a devastating pulmonary disease caused by mutation of tuberous sclerosis complex 1/2 (TSC1/2), resulting in mammalian target of rapamycin complex 1 (mTORC1) activation, which chiefly affects young women of childbearing age." (PMID 36543771, 2022). "TSC and lymphangioleiomyomatosis (LAM) are caused by biallelic mutations of the TSC1 or TSC2 genes, coding for tumor suppressors hamartin and tuberin, respectively." (PMID 34806651, 2021). "show in TSC1- or TSC2-deficient lymphangioleiomyomatosis patient derived cells that BI2536 moderately inhibits autophagy." (PMID 28102733, 2017). "To attempt to develop a mouse model of Shagreen patch, cephalic patch, facial angiofibroma, ungual fibroma, renal angiomyolipoma, and/or lymphangioleiomyomatosis, we used an Fsp-cre transgene to drive loss of Tsc1 in fibroblasts in mice in vivo." (PMID 27907099, 2016). "Lymphangioleiomyomatosis (LAM) is a rare lung-metastasizing neoplasm caused by the proliferation of smooth muscle-like cells that commonly carry loss-of-function mutations in either the tuberous sclerosis complex 1 or 2 (TSC1 or TSC2) genes." (PMID 26167915, 2015). "Current evidence indicates that lymphangioleiomyomatosis (LAM) arises from TSC1/2 gene mutations driving constitutive activation of the mTOR signaling pathway, which promotes dysregulated proliferation of neoplastic LAM cells." (PMID 41204185, 2025). "Lymphangioleiomyomatosis (LAM), common in women of childbearing age with TSC1/2 mutations, shows multiple nodules of immature smooth muscle and perivascular epithelial cells." (PMID 39867882, 2024). "A rare lung disease, lymphangioleiomyomatosis (LAM), is caused by a loss-of-function mutation in the TSC1/2 gene, resulting in lung tissue damage through proliferation, growth, and invasion of LAM cells." (PMID 38515456, 2024). "Genetic mutations or alterations in TSC1/2 have an important role not only in various cancers but also in some slow-growing neoplasms like lymphangioleiomyomatosis (LAM) or angiomyolipoma (AML)." (PMID 37443747, 2023). "Lymphangioleiomyomatosis (LAM) is a progressive cystic lung disease caused by tuberous sclerosis complex 1/2 (TSC1/2) gene mutations in pulmonary mesenchymal cells, resulting in activation of the mechanistic target of rapamycin complex 1 (mTORC1)." (PMID 38127441, 2023). "Lymphangioleiomyomatosis (LAM) is a rare progressive disease, characterized by mutations in the tuberous sclerosis complex genes (TSC1 or TSC2) and hyperactivation of mechanistic target of rapamycin complex 1 (mTORC1)." (PMID 35181635, 2022). "Mutations or loss of TSC1/2 lead to hyperactivation of mTORC1 signaling and have been associated with many human disorders, such as lymphangioleiomyomatosis (LAM) and autism." (PMID 33670113, 2021). "Lymphangioleiomyomatosis (LAM) mutations in TSC1 or TSC2 genes result in the activation of the mTOR complex 1 (mTORC1)." (PMID 33922083, 2021). "Lymphangioleiomyomatosis (LAM) is a devastating lung disease caused by inactivating gene mutations in either TSC1 or TSC2 that result in hyperactivation of the mechanistic target of rapamycin complex 1 (mTORC1)." (PMID 32078667, 2020). "Lymphangioleiomyomatosis (LAM) is a rare fatal cystic lung disease due to bi-allelic inactivating mutations in tuberous sclerosis complex (TSC1/TSC2) genes coding for suppressors of the mechanistic target of rapamycin complex 1 (mTORC1)." (PMID 33159078, 2020). "Tuberous Sclerosis Complex (TSC) and Lymphangioleiomyomatosis (LAM) are caused by inactivating mutations in TSC1 or TSC2, leading to mTORC1 hyperactivation." (PMID 30816188, 2019).
lymphangioleiomyomatosis (continued). "However, immunohistochemical stains demonstrated tumor positivity for HMB45, desmin, and Cathepsin K, and genetic testing revealed a TSC1 variant, leading to a definite diagnosis of uterine PEComa with lymphangioleiomyomatosis (LAM)-like features." (PMID 41755808, 2026). "Lymphangioleiomyomatosis (LAM) is a rare cystic lung disease primarily affecting women, driven by TSC1 or TSC2 mutations that lead to constitutive mTORC1 activation and progressive respiratory failure." (PMID 41180734, 2025). "Mutations in TSC1 and TSC2 genes located on chromosomes 9 and 16 have been identified in patients with lymphangioleiomyomatosis." (PMID 41383536, 2025). "Similarly, patients with a progressive lung disease, lymphangioleiomyomatosis (LAM), can have sporadic LAM (S-LAM) with TSC1/TSC2 variants, probably two somatic hits, isolated to the affected tissue." (PMID 38540392, 2024). "Lymphangioleiomyomatosis (LAM), a progressive pulmonary disease exclusively affecting females, is caused by defects or mutations in the coding gene tuberous sclerosis complex 1 (TSC1) or TSC2, causing the mammalian target of rapamycin complex 1 (mTORC1) activation and autophagy inhibition." (PMID 36543771, 2022). "Lymphangioleiomyomatosis is associated with the mutational inactivation of the tuberous sclerosis gene complex (TSC), TSC1 and TSC26,7." (PMID 26282580, 2015). "Comprehensive diagnostic evaluation – including fundoscopy, brain MRI, echocardiography, and TSC1/2 genetic testing (negative for mutations) – confirmed sporadic lymphangioleiomyomatosis (LAM) with giant renal angiomyolipomas (AMLs)." (PMID 41204185, 2025). "Tuberous Sclerosis Complex (TSC) is caused by TSC1 or TSC2 mutations, leading to hyperactivation of mechanistic target of rapamycin complex 1 (mTORC1) and lesions in multiple organs including lung (lymphangioleiomyomatosis) and kidney (angiomyolipoma and renal cell carcinoma)." (PMID 38195686, 2024). "Indeed, loss of Tsc1 has been shown to alter Notch and alter the progression of NSC-like cells in lymphangioleiomyomatosis and along the neural tube." (PMID 38107199, 2023). "Loss of Tsc1 in fibroblasts in mice does not lead to a model of angiomyolipoma or lymphangioleiomyomatosis." (PMID 27907099, 2016). "The aim of our study was to elucidate the landscapes of genetic alterations of TSC1 and TSC2 as well as other possible non-TSC1/2 in Lymphangioleiomyomatosis (LAM) patients." (PMID 31856217, 2019). "Mutations in TSC1 and TSC2 have been reported in a variety of neoplasms and benign tumors including pulmonary lymphangioleiomyomatosis (LAM), perivascular epitheloid cell tumors (PEComa), urothelial carcinomas, renal cell carcinoma and hepatocellular carcinomas." (PMID 28302097, 2017). "Additionally, our results indicate that TSC1/TSC2 alterations, including CN-LOH, are nearly universally present in SEGAs, consistent with TSC1/TSC2 molecular findings seen in other TSC-related tumors e.g. renal angiomyolipomas (AMLs) and lymphangioleiomyomatosis (LAM)." (PMID 29221145, 2017).